SOCS3 (suppressor of cytokine signaling 3)
Diseases named in the same sentence as SOCS3 in open-access papers (continued):
Sharing a sentence is not in itself a finding about the gene and the disease.
endotoxemia (6 papers, 2011 to 2025). "Here, we show that loss of endothelial expression of the IL-6 pathway inhibitor SOCS3 promoted a type I IFN–like (IFNI-like) gene signature in response to endotoxemia in mouse kidneys and brains." (PMID 40956626, 2025). "In summary, we demonstrate that endothelial SOCS3 promotes vascular homeostasis and survival in a murine model of endotoxemia." (PMID 34138760, 2021).
Glucose intolerance (6 papers, 2012 to 2021). Glucose intolerance (GI) can be defined as dysglycemia that comprises both prediabetes and diabetes. "Furthermore, overexpression of SOCS3 decreased the hepatic expressions of IRS1, IRS2 and PI3K, and resulted in glucose intolerance and decrease glucose uptake." (PMID 29743495, 2018).
lung injury (6 papers, 2019 to 2025). "In this study, we further investigated whether lidocaine can mediate AMPK activation and SOCS3 expression in LPS-induced acute lung injury model and whether lidocaine can alleviate LPS-mediated pulmonary edema, coagulation dysfunction, and inflammatory response." (PMID 34804364, 2021). "In acute lung injury mouse model, LHQWG acted as a potent epithelial protector, significantly reducing NF-κB levels, reversing the SOCS3 expression in macrophages, and blocking proapoptotic communication between macrophages and alveolar epithelial cells." (PMID 34400884, 2021).
medulloblastoma (6 papers, 2016 to 2023). A malignant, invasive embryonal neoplasm arising from the cerebellum. "SOCS3 proteins are accumulated in the distal ends of axon-like processes of resveratrol-differentiated medulloblastoma cells." (PMID 28035977, 2016). "Therefore, it would be possible that SOCS3 level is reduced in resveratrol-treated medulloblastoma cells with suppressed STAT3 signaling." (PMID 28035977, 2016). "In resveratrol-suppressed medulloblastoma cells with STAT3 downregulation and decreased incidence of STAT3 nuclear translocation, PIAS3 is upregulated, the SHP2 level remains unchanged and SOCS3 is downregulated." (PMID 28035977, 2016). "The results revealed the general reductions of p-SHP2, SOCS3 and especially PIAS3 levels in the three medulloblastoma subtypes with frequent p-STAT3 nuclear translocation." (PMID 28035977, 2016). "It is found that upon resveratrol treatment, PIAS3 is up-regulated and translocalized in nuclei, SOCS3 level is reduced and SHP2 remains unchanged in the three medulloblastoma cells so far checked." (PMID 28035977, 2016). "Alternatively, it would be more convincing if the levels of SHP2, SOCS1/SOCS3 and/or PIAS3 are altered accordingly in medulloblastoma cells with suppressed STAT3 signaling." (PMID 28035977, 2016). "A recent study has shown a relationship among AMBRA1, CUL4–DDB1 complex, and STAT3 in medulloblastoma (MB) stem cells, demonstrating that AMBRA1, through its direct interaction with the CUL4–DDB1 complex, is involved in the degradation of SOCS3, an inhibitor of STAT3 activity." (PMID 37106439, 2023). "SHP2, SOCS3 and PIAS3 are known as the negative regulators of STAT3 signaling, while their relevance to frequent STAT3 activation in medulloblastomas remains unknown." (PMID 28035977, 2016). "Therefore, the resveratrol-treated medulloblastoma cells would be an ideal model to evaluate the role of SHP2, SOCS3 or PIAS3 in regulating STAT3 signaling." (PMID 28035977, 2016). "Inverse correlation could be established between p-SHP2 (R = −0.35; p = 0.029), SOCS3 (R = 0.495; p = 0.001) or PIAS3 expression (R = −0.352; p = 0.020) and p-STAT3 nuclear translocation in the classic medulloblastomas." (PMID 28035977, 2016).
renal cell carcinoma (6 papers, 2014 to 2025). "Similarly, silencing of SOCS3 increases the susceptibility of renal cell carcinomas to IFN." (PMID 30186768, 2018). "In contrast, inhibition of SOCS3 promoted IFN-α-induced cell death and growth suppression in renal cell carcinoma." (PMID 25658748, 2015). "A study showed the association of the lack of Stat1, Tyk2, and Jak1 expression and defective Jak-Stat activation with resistance to IFN-α in renal cell carcinoma cells, while IFNAR1 and SOCS3 proteins were not involved." (PMID 30186768, 2018).
ZIKV infection (6 papers, 2019 to 2021). "In the current study, both SOCS1 and SOCS3 transcript levels were significantly elevated upon ZIKV infection, and the induction levels were similar for the African and Asian lineages." (PMID 32120897, 2020). "Our result suggests that ZY13 administration downregulates the expression of Axl, SOCS1 and SOCS3 at early stage post ZIKV infection." (PMID 32849457, 2020). "In addition, western blot results confirmed the upregulation of SOCS1 and SOCS3 protein levels triggered during the early phases of ZIKV infection." (PMID 32120897, 2020). "In contrast, SOCS3 expression was upregulated following ZIKV infection at 24 hpi." (PMID 32120897, 2020). "Upon ZIKV infection, the expression levels of SOCS1 and SOCS3 were upregulated in a manner dependent on post-infection timepoints." (PMID 32120897, 2020). "ZIKV infection also increased expression of mRNAs for both IFNLR1 and IL10RB components of the IFNλ heterodimeric receptor complex and the SOCS1 and SOCS3 negative regulators of IFN signaling." (PMID 31289325, 2019). "As ZIKV infection resulted in the upregulation of both SOCS1 and SOCS3 expression, SOCS1 or SOCS3 was overexpressed in A549 cells in order to further evaluate the functional roles of SOCS1 and SOCS3 in viral replication." (PMID 32120897, 2020). "SOCS1 and SOCS3 expression increased at 4 hpi and continued to increase at later timepoints; a finding which indicates the early induction of SOCS expression subsequent to ZIKV infection." (PMID 32120897, 2020). "Our studies reveal that during ZIKV infection, recognition of viral RNA by TLR3 enhances the production of inflammatory cytokines and suppresses the interferon response triggered by RIG-I-like receptors (RLR) in a SOCS3-dependent manner, thus facilitating virus replication." (PMID 33658344, 2021). "Indeed, ZIKV infection under conditions of antibody-mediated sequestration of IL-6, which was released from the cells into the culture supernatant, resulted in ∼3-fold-enhanced STAT1 phosphorylation (top blot), whereas STAT3 phosphorylation and SOCS3 expression were significantly reduced." (PMID 33658344, 2021). "Therefore, to investigate whether Axl kinase augments ZIKV infection of human SC by negatively regulating antiviral response, we first evaluated the effect of R428 treatment on protein levels of STAT1/p-STAT1 (phosphorylated STAT1), SOCS1, and SOCS3." (PMID 31311882, 2019).
acute myeloid leukemia (5 papers, 2016 to 2022). Acute myeloid leukemia (AML) is a group of neoplasms arising from precursor cells committed to the myeloid cell-line differentiation. "Other studies showed that STAT3 signal transduction pathway induces SOCS-3 in acute myeloid leukemia cells and in rat astrocytes." (PMID 29234375, 2017). "Furthermore, in vitro studies have shown that 5-Aza and TSA can reactivate the SOCS-3 gene in acute myeloid leukemia (AML) cells." (PMID 34319031, 2021). "It has been shown that BRD9 depletion (at the mRNA and protein level) upregulates SOCS3, which, in turn, inhibits STAT5, reducing JAK-STAT pathway activation in acute myeloid leukaemia." (PMID 34944438, 2021).
Alzheimer disease (5 papers, 2020 to 2025). A progressive, neurodegenerative disease characterized by loss of function and death of nerve cells in several areas of the brain leading to loss of cognitive function such as memory and language. "In the context of Alzheimer’s disease (AD), studies have explored the expression of SOCS3 in the brains of AD patients." (PMID 37916989, 2023). "In Alzheimer's disease models, this pathway has been shown to attenuate Aβ‐induced neurotoxicity and reduce tau hyperphosphorylation, whereas in our SCI model it mediates bilirubin's anti‐inflammatory effects through SOCS3 induction, a critical suppressor of pro‐inflammatory pathways." (PMID 40958634, 2025).
chronic hepatitis C (5 papers, 2012 to 2016). "SOCS-3 is a gene involved in the interferon signaling pathway and it is associated with poorer treatment outcome in patients with chronic hepatitis C viral genotype 1." (PMID 25821463, 2015). "SOCS3 was induced by HCV core protein and maintained at relatively high levels in chronic hepatitis C patients." (PMID 22745742, 2012).
endometrial cancer (5 papers, 2010 to 2022). Primary or metastatic malignant neoplasm involving the endometrium (mucous membrane that lines the endometrial cavity). "An increased cellular proliferation of endometrial cancer was shown to be linked to UHRF1-mediated H3R8 di-methylation of the SOCS3 and 3OST2 promoter." (PMID 36077796, 2022). "This suggests that SOCS3 has different functions in cycling endometrium compared to endometrium from postmenopausal women and endometrial cancer." (PMID 20553623, 2010). "It further demonstrated that IL11's main endometrial signalling molecules, pSTAT3 and SOCS3, were produced by endometrial cancer cells." (PMID 20553623, 2010). "We compared IL11, IL11Rα, pSTAT3 and SOCS3 protein in human endometrial carcinomas of varying histologic grades with endometrium from postmenopausal and cycling women." (PMID 20553623, 2010). "The present study suggests that IL11, along with its specific receptor and downstream signalling molecules pSTAT3 and SOCS3, are likely to play a complex role in the progression of endometrial carcinoma." (PMID 20553623, 2010). "It indicates that IL11, along with its specific receptor, IL11Rα, and downstream signalling molecules, STAT3 and SOCS3, are likely to play a role in the progression of endometrial carcinoma." (PMID 20553623, 2010). "It was speculated that methylation-silenced SOCS3 plays a key role in the pathogenesis of endometrial carcinoma." (PMID 29662621, 2018). "SOCS3 localised primarily to the endometrial cancer epithelium in all grades of carcinomas." (PMID 20553623, 2010). "IL11 was shown to signal via pSTAT3 and SOCS3 in human endometrial cancer cell lines." (PMID 20553623, 2010). "However, since endometrial cancer affects predominantly post-menopausal women, we compared the levels of IL11, IL11Rα, pSTAT3 and SOCS3 in endometrial cancer tissue to endometrial tissue from post-menopausal." (PMID 20553623, 2010). "By contrast IL11 weakly stimulated SOCS3 protein at 100 ng/ml in the carcinoma HEC-1A and Ishikawa cells possibly suggesting reduced sensitivity in endometrial cancer cells." (PMID 20553623, 2010). "The effect of IL11 on pSTAT3/STAT3 and SOCS3 protein abundance in endometrial cancer cell lines and non-cancer endometrial epithelial cells was determined by Western blot." (PMID 20553623, 2010). "IL11, IL11 receptor(R) α, phosphorylated (p) STAT3 and SOCS3 were examined by immunohistochemistry in endometrial carcinomas and in control endometrium from postmenopausal women and normal cycling women." (PMID 20553623, 2010). "In the present study SOCS3 staining intensity was absent or very minimal in tumour epithelial cells in the Grade 3 cancer specimens perhaps similarly indicating a reduced sensitivity to SOCS3 in endometrial cancers although this remains to be determined." (PMID 20553623, 2010).
eosinophilia (5 papers, 2012 to 2025). "Moriwaki and colleagues found that down-regulation of Socs3 in ovalbumin sensitized mice caused attenuation of eosinophilia and airway hyperresponsiveness generated by ovalbumin challenge." (PMID 23209423, 2012). "Studies in allergic mouse models have shown that overexpression of SOCS3 in T cells enhances allergic responses whereas its silencing reduces airway hyperresponsiveness, eosinophilia, and other allergic symptoms." (PMID 40104138, 2025). "Transient knockdown of SOCS3 by naked siRNA in chronic asthmatic mice has led to a decrease in lung eosinophilia, as well as a significant reduction of AHR and mucous in the airways, therefore improving chronicity and remodelling." (PMID 24637581, 2014). "Our group has developed an intranasal therapy to deliver a pool of SOCS3 siRNA into the lungs of chronic asthmatic mice, leading to a decrease in lung eosinophilia as well as a significant reduction of AHR and mucous in the airways, which in turn improves chronicity and remodeling." (PMID 25764157, 2015).
head and neck cancer (5 papers, 2010 to 2024). A primary or metastatic malignant neoplasm affecting the head and neck. "Consistently, hyper-methylation of the SOCS3 promoter is found in 90% of head and neck cancer, suggesting that SOCS3 inactivation induced by methylation gene may be an early event in these cancers." (PMID 38975347, 2024).
heart failure (5 papers, 2020 to 2024). Inability of the heart to pump blood at an adequate rate to meet tissue metabolic requirements. "In all CHF patients, higher TNF, IL-10, SOCS1 and SOCS3 gene expression was associated with severity of heart failure according to MR-proANP (r = 0.4, p < 0.03, r = 0.39, p < 0.03, r = 0.45, p < 0.03 and r = 0.45, p < 0.02, respectively)." (PMID 38337428, 2024). "The probability of heart failure was significantly increased in patients with high expression of SOCS3 and NRXN1, while the expression of CDK6 and SMAD4 was significantly reduced in patients without heart failure." (PMID 33224271, 2020). "This outcome was supported by the current study, which demonstrated that SOCS3 was simultaneously upregulated in MI and heart failure patients." (PMID 33224271, 2020). "Moreover, cardiac-specific deletion of the myocardial suppressor of cytokine signaling-3 (SOCS-3), the endogenous feedback inhibitor of STAT3, results in reduced myocardial remodelling and severity of heart failure in the 14-day post-infarcted mouse heart." (PMID 38256208, 2024). "Furthermore, Suppressor of cytokine signaling-3 (SOCS3) was found to target GRP78 ubiquitination for proteasomal degradation, thereby blocking ER stress and mitophagy pathways in cardiac hypertrophy, which could potentially prevent heart failure." (PMID 37605113, 2023).
ischemia (5 papers, 2019 to 2023). A hypoperfusion of the BLOOD through an organ or tissue caused by a PATHOLOGIC CONSTRICTION or obstruction of its BLOOD VESSELS, or an absence of BLOOD CIRCULATION. "Based on our findings, we suggest that paeoniflorin is potentially effective in alleviating radiation enteritis via the activation of the Gas6/Axl/SOCS3 axis and subsequent reduction in intestinal inflammation and ischemia." (PMID 35359871, 2022). "We previously demonstrated that myocardial stress, such as pressure overload and ischemia, rapidly and strongly induce SOCS3." (PMID 34292971, 2021). "Paeoniflorin, a pinane monoterpene bitter glycoside, could increase Suppressor of cytokine signaling 3 (SOCS3) expression, active the Gas6/Axl/SOCS3 axis and subsequent reduction in intestinal inflammation and ischemia." (PMID 37063268, 2023). "Here, we provide the first evidence that PF could alleviate RE by activating the Axl/SOCS3 axis to reduce intestinal inflammation and ischemia." (PMID 35359871, 2022). "Furthermore, we found that miR-30b, a molecule which is required for IL-21-induced angiogenesis under ischemia, also increases STAT3 activation with reduced SOCS3 expression." (PMID 35008699, 2021).
lymph node metastasis (5 papers, 2015 to 2023). "However, statistically significant correlations were found with lymph node metastasis, overall survival rate and postoperative recurrence (P < 0.05) for both SOCS3 and A20." (PMID 26485275, 2015).
mastitis (5 papers, 2013 to 2022). Inflammation of breast tissue during lactation or postpartum due to an obstructed duct or infection. "Among these, seven genes (CXCR1, HCK, IL1RN, MMP9, S100A9, GRO1, and SOCS3) were identified as the hub genes and these can be explored as potential candidate genes for mastitis susceptibility and resistance." (PMID 35723402, 2022). "It is highly recommended that further polymorphisms in STAT1 and SOCS3 and their associations with milk production and mastitis resistance traits be found out." (PMID 33202860, 2020). "Among these, seven genes—CXCR1, HCK, IL1RN, MMP9, S100A9, GRO1, and SOCS3—were identified as the hub genes (highly connected genes) for mastitis susceptibility and resistance, and were subjected to protein-protein interaction (PPI) network and gene regulatory network construction." (PMID 35723402, 2022). "Further study is highly recommended to find out the specific variants in SOCS3 that interact with STAT5 and JAK2 during mastitis development and milk production in dairy cattle." (PMID 33202860, 2020). "SOCS3 negatively regulates IL-6, which is the key player in immune regulation and has an important role in mastitis resistance." (PMID 32630405, 2020). "Interestingly, BIRC5 and SOCS3 are located in the region of QTL markers associated with somatic cell score (SCS) in NRF, and elevated SCS is often an indicator of subclinical mastitis in cattle infected with S. aureus." (PMID 24341851, 2013). "This evidence shows that SOCS3 might have a potential role in mastitis development in dairy cattle." (PMID 33202860, 2020). "The most important overexpressed genes in cows with mastitis were GRO1, CXCR1, SOCS3, S100A9, MMP9, HCK, and IL1RN, which were hub genes (highly connected genes) involved in mastitis in this study." (PMID 35723402, 2022). "Genes such as NFKBIA, SOCS3, and PIM1, which play a key role in the development of mastitis, were noted to be up-regulated in the S. aureus-infected mammary gland tissue of dairy cattle." (PMID 32630405, 2020). "The upregulation of SOCS3 in bovine mammary epithelial cells inhibits the activation of JAK2 and STATs genes, which promotes mastitis development and reduces the lactational performance of dairy cattle." (PMID 33202860, 2020). "The authors further supposed that SOCS3 could negatively regulate the JAK-STAT pathway, which might be one of the reasons for its critical role in mastitis development." (PMID 33202860, 2020). "Furthermore, it is suggested that the interactive mechanism of SOCS3, STATs, and JAK2, STAT5A, and STAT5B during milk production and mastitis development should be considered in future rodent-knockout research models." (PMID 33202860, 2020).
pneumonia (5 papers, 2022 to 2025). An acute, acute and chronic, or chronic inflammation focally or diffusely affecting the lung parenchyma, caused by an infection in one or both of the lungs (by bacteria, viruses, fungi, or mycoplasma.). "Using PCR-DNA sequence verdicts, the TLR2 (354 bp), CLEC4E (443 bp), PTX3 (363 bp), CXCL8 (300 bp), SOCS3 (480 bp) and IL15RA (378 bp) genes were found to have different SNPs in the amplified DNA bases linked to pneumonia." (PMID 40559821, 2025). "This study used a PCR-DNA sequencing technique to characterize the immunological (TLR2, CLEC4E, PTX3, CXCL8, SOCS3 and IL15RA) genes in ewes with pneumonia and healthy ewes." (PMID 40559821, 2025). "By means of the miR-455-5p/SOCS3 pathway,GAS5 boosts M1 macrophage polarization in adolescent pneumonia." (PMID 35880572, 2022).